PIWIL4 (piwi like RNA-mediated gene silencing 4)
Diseases named in the same sentence as PIWIL4 in open-access papers (continued):
Sharing a sentence is not in itself a finding about the gene and the disease.
colorectal cancer (2 papers, 2021 to 2022). A primary or metastatic malignant neoplasm that affects the colon or rectum. "Among them, only PIWIL4 was markedly overexpressed in colorectal cancer and positively related with LINC00857 expression by bioinformatic analysis." (PMID 36160408, 2022). "This offered a powerful rationale for the clinical discovery of drugs targeting PIWIL4 for colorectal cancer treatment." (PMID 36160408, 2022). "Our study further elucidated the relevance of PIWIL4 expression with the immune features of colorectal cancer, which was in accordance with the roles of LINC00857." (PMID 36160408, 2022). "These discoveries could likely help to illuminate the roles of LINC00857/PIWIL4 axis in colorectal tumorigenesis and development, provide a novel perspective for colorectal cancer immunotherapy, and make it possible to achieve more precise and efficient immunotherapy in the clinic." (PMID 36160408, 2022). "To probe the possible roles of PIWIL4 in colorectal cancer, we implemented GSEA of TCGA datasets according to the PIWIL4 expression status in COAD tissues." (PMID 36160408, 2022). "Screening by weighted gene co-expression network analysis determined PIWIL4 as a target of LINC00857, which also performed an immunosuppressive role in colorectal cancer." (PMID 36160408, 2022).
intrahepatic cholangiocarcinoma (2 papers, 2021 to 2025). A carcinoma that arises from the intrahepatic bile duct epithelium in any site of the intrahepatic biliary tree. "Furthermore, the PIWIL4/SUPT5H complex has been identified as a promising prognostic biomarker for predicting clinical outcomes and immune microenvironment features in intrahepatic cholangiocarcinoma." (PMID 41208974, 2025).
ovarian carcinoma (2 papers, 2020 to 2023). A malignant neoplasm originating from the surface ovarian epithelium. "PIWIL4 role in tumorigenesis is controversial; high expressions of PIWIL4 are found in colorectal, cervical, gastric, and ovarian cancer." (PMID 37568728, 2023). "For the two ovarian cancer samples, dpCNV gets 225 cytobands and 128 cytobands, 285 genes and 529 genes overlapped with the COSMIC database, respectively, in which there are many important tumor driver genes corresponding to ovarian cancer, such as PUM1, GOLPH3L, PIWIL4, and KNDC1." (PMID 33519925, 2020).
pancreatic cancer (2 papers, 2020 to 2022). "We aimed to discover PIWIL3- and PIWIL4-modulated piRNAs and determine their potential mechanisms in pancreatic cancer and the clinical implications." (PMID 36555927, 2022). "Finally, PIWIL3 and PIWIL4 evaluation in human pancreatic cancer samples showed that patients with low levels of PIWIL4 protein expression presented poor prognosis." (PMID 32357464, 2020). "PIWIL3 or PIWIL4 was downregulated in pancreatic cancer-derived cell lines or in a non-tumour cell line." (PMID 36555927, 2022). "In the present study, we evaluated PIWIL1, PIWIL2, PIWIL3 and PIWIL4 expression in pancreatic cancer-derived cell lines and in one non-tumor cell line as healthy control." (PMID 32357464, 2020). "However, PIWIL3’s and PIWIL4’s role in carcinogenesis is rather controversial, and their clinical implication in pancreatic cancer has not yet been investigated." (PMID 32357464, 2020).
prostate carcinoma (2 papers, 2020 to 2023). A carcinoma that arises from epithelial cells of the prostate gland. "In prostate cancer, piR-31470 formed a complex with piwi-like RNA-mediated gene silencing 4 (PIWIL4)." (PMID 32709863, 2020).
acute myeloid leukemia (1 paper, 2024). Acute myeloid leukemia (AML) is a group of neoplasms arising from precursor cells committed to the myeloid cell-line differentiation. "Specifically, PIWIL4 is highly expressed in multiple cancers with the highest levels found in acute myeloid leukemia (AML), an aggressive malignancy propagated by a population of leukemia stem cells (LSCs)." (PMID 39188528, 2024).
atypical ductal hyperplasia (1 paper, 2020). Atypical ductal hyperplasia is an atypical proliferative lesion that falls in between the continuum from normal hyperplasia to low grade ductal carcinoma in situ. "PIWIL2 and PIWIL4 were downregulated in pre-invasive breast lesions such as atypical ductal hyperplasia (PIWIL2 (30%) and PIWIL4 (20%)) and ductal carcinoma in situ (PIWIL2 (40%) and PIWIL4 (40%))." (PMID 33008024, 2020).
bacterial pneumonia (1 paper, 2022). Acute infection of the lung parenchyma caused by bacteria (e.g., Streptococcus pneumoniae, Haemophilus influenzae, Chlamydia pneumoniae, Mycoplasma pneumoniae, and Legionella pneumophila). "A recent study of bacterial pneumonia using a knockout mouse for MIWI2, the mouse homologue of human PIWIL4, revealed an important role of this piwi protein in lung innate immune response." (PMID 36158569, 2022).
benign ovarian tumors (1 paper, 2014). "In order to investigate a possible role of this pathway in EOC, we performed semi-quantitative RT-PCR to investigate the expression of PIWIL1, PIWIL2, PIWIL3, PIWIL4 and MAEL in advanced stage serous EOC (n = 25), benign ovarian tumors (n = 19) and normal ovarian tissue (n = 8)." (PMID 24932571, 2014).
ductal carcinoma in situ (1 paper, 2020). "We observed progressive PIWIL2 and PIWIL4 downregulation with absence or very slight nuclear staining (HScore = 0–0.5) in atypical ductal hyperplasia (PIWIL2 (30%, n = 3) and PIWIL4 (20%, n = 2)) and ductal carcinoma in situ (PIWIL2 (40%, n = 4) and PIWIL4 (40%, n = 4))." (PMID 33008024, 2020).
endometrial cancer (1 paper, 2015). Primary or metastatic malignant neoplasm involving the endometrium (mucous membrane that lines the endometrial cavity). "In this study, we confirmed that the expression of Piwi proteins (Piwil1, Piwil2, Piwil13, and Piwil4) are different in endometrial cancer cell lines and we mainly focused on the role of Piwil1 in endometrial cancer." (PMID 26506848, 2015).
fibrosarcoma (1 paper, 2023). A malignant mesenchymal fibroblastic neoplasm affecting the soft tissue and bone. "Overexpression of PIWIL4 induced G2/M arrest and apoptosis in fibrosarcoma cells, whereas knockdown of PIWIL4 enhanced cell proliferation, metastasis, and invasion." (PMID 38031146, 2023). "Only 5% of fibrosarcoma patients show high PIWIL4 expression, which positively correlates with survival, disease-free survival, disease-specific survival, and progression-free survival." (PMID 38031146, 2023).
hyper-IgE syndrome (1 paper, 2023). A condition that is characterized by elevated serum IgE, dermatitis, and respiratory infections. "The 12-year-old hyper-IgE syndrome patient (patient 5) presented approximately twice as many PIWIL4+ cells as the XIAP deficiency patient (patient 6), while the 7-year-old ß-thalassemia major patient whose tissue was applied for the organ culture had the highest PIWIL4+ cell count (patient 2)." (PMID 36766757, 2023).
leukemia (1 paper, 2024). A malignant (clonal) hematologic disorder, involving hematopoietic stem cells and characterized by the presence of primitive or atypical myeloid or lymphoid cells in the bone marrow and the blood. "PIWIL4 overexpression could lead to the emergence of LSCs, driving leukemia propagation and maintenance." (PMID 39188528, 2024). "Here, we present an additional perspective on the potential role of PIWIL4 contributing to the differentiation status of AML and the emergence of LSCs responsible for leukemia development and maintenance." (PMID 39188528, 2024).
lung carcinoma (1 paper, 2020). "Previous studies have reported that the expression IGF2BP1, TLR8, PIWIL4, and GAPDH were associated with tumorigenesis and progression of lung cancer patients, which consistent with our results." (PMID 32087603, 2020). "However, the antibody staining level of TLR8, PIWIL4, and ZC3H12C were relatively reduced in lung cancer tissue." (PMID 32087603, 2020).
lymph node metastasis (1 paper, 2015). "The expression of Piwil1, Piwil2, Piwil13, and Piwil4 were positively correlated with T stage, lymph node metastasis and clinical TNM and patients with higher expression had shorter survival time." (PMID 26506848, 2015).
pneumonia (1 paper, 2024). An acute, acute and chronic, or chronic inflammation focally or diffusely affecting the lung parenchyma, caused by an infection in one or both of the lungs (by bacteria, viruses, fungi, or mycoplasma.). "In pneumonia, PIWIL2 and PIWIL4 are upregulated in response to endoplasmic reticulum (ER) stress, and MIWI2 modulates immune responses in multiciliated airway epithelial cells in mice." (PMID 39717847, 2024).
respiratory infections (1 paper, 2025). "In conclusion, our findings suggest that Miwi2/Piwil4 acts as a potential host susceptibility factor for severe respiratory infections." (PMID 40241756, 2025). "Our study identifies Miwi2/Piwil4 as a potential factor influencing susceptibility to severe respiratory infections." (PMID 40241756, 2025).
retinal degeneration (1 paper, 2023). Degeneration of the retina. "Concerning DP, MBD2 was involved in the formation of the eye, interacting both with HK2 and HIF1A, while PIWIL4 displayed an interaction with DICER1, which was involved in retinal degeneration." (PMID 37359372, 2023).
skin cancer (1 paper, 2016). "PIWIL1,2,3 and PIWIL4 have been found to be mutated in skin cancer." (PMID 27183847, 2016).
ß-thalassemia (1 paper, 2023). "Both the 7-year-old patients with thalassemia and the 12-year-old XIAP deficiency patient show the same difference between the DDX4+ and the PIWIL4+ cells, so it can be assumed that the SPG differentiation, including proliferation of the SPG, is already more advanced here." (PMID 36766757, 2023).
cancer (34 papers, 2010 to 2024). A tumor composed of atypical neoplastic, often pleomorphic cells that invade other tissues. "PIWIL3 is associated with metastasis and proliferation, while PIWIL4 is also observed to have an impact on other processes such as cell cycle, apoptosis, and regulation of cancer immunology." (PMID 39596284, 2024). "However, other studies reported that low PIWIL4 expression is associated with a poor prognosis in different cancer types." (PMID 37568728, 2023). "As anticipated, PIWIL4 exhibited overexpression in blood samples derived from cancer patients compared to their normal counterparts." (PMID 39188528, 2024). "PIWIL4 upregulation was identified as a critical biomarker in this cancer, proportional to patient survival." (PMID 38031146, 2023). "In previous studies, PIWIL1, PIWIL2, and PIWIL4 have been reported to function in cancer cell proliferation, metastasis, and invasion." (PMID 38033031, 2023). "A possible role for the interaction between pVHL30 and PIWIL4 in the formation of these two cancers is at least fascinating and will require further investigation." (PMID 35205757, 2022). "The immunoprecipitation of PIWIl4 (Hiwi2) from MDAMB231 cancer cells revealed the presence of the following tRFs: 5′ tRFGlu(CUC), tRFLys(TTT) and tRFVal(ACC), which are predominantly derived from processed tRNAs." (PMID 35409004, 2022). "Normally, PIWIL4 is expressed in various human tissues, but it is considerably upregulated in cancer tissues." (PMID 36324572, 2022). "A systematic review and meta-analysis showed that PIWI family proteins have the potential to indicate the prognosis of various cancer, and lower PIWIL4 expression levels indicate worse prognosis in cancer." (PMID 34876138, 2021). "In most of malignant tumors belonging to this panel, we observed an expression profile comparable to IBCs associating variable PIWIL2 and PIWIL4 genes downregulation and an emerging aberrant expression of PIWIL1 and PIWIL3." (PMID 33008024, 2020). "The human genome encodes four PIWIL genes, known as PIWIL1 (HIWI), PIWIL2 (HILI), PIWIL3 (HIWI3), and PIWIL4 (HIWI2); some of which were found to be highly expressed in several human cancers." (PMID 32204558, 2020). "Other research highlighted that PIWIL3 and PIWIL4 presented oncogenic potential in several types of cancers." (PMID 32357464, 2020). "On the other hand, PIWIL2 and PIWIL4 show low expression in many normal tissues and are upregulated in several cancer types, while PIWIL3 is almost undetectable in all tissues considered, except germline." (PMID 31694219, 2019). "PIWIL1, PIWIL3, and PIWIL4 act as intrinsic regulators of the self-renewal capacity of germ line and hematopoietic stem cells, and are believed to be involved in cancer development." (PMID 28422722, 2017). "A limited number of studies analyzed PIWIL4 expression in cancer." (PMID 38303021, 2024). "Despite the growing interest in PIWIL4’s role in cancer its expression dynamics during myeloid cell differentiation remain unclear." (PMID 39188528, 2024). "Furthermore, the expression levels of PIWIL4 were significantly higher in cancer than in adjacent mucosa, while EPHB2 expression was higher in adjacent normal tissues than in tumorous tissues." (PMID 37958942, 2023). "The LINC00857/PIWIL4 axis may be predictive biomarkers for immunotherapy and valuable molecular targets for malignant tumors." (PMID 36160408, 2022). "LINC00857/PIWIL4 axis may be predictive biomarkers for immunotherapy and valuable molecular targets for malignant tumors." (PMID 36160408, 2022). "Interestingly, combining the bioinformatics and qPCR verification, we eventually discovered that LINC00857 probably exert its oncogenic effects by mediating PIWIL4 expression, which presented oncogenic potential in multiple cancer types." (PMID 36160408, 2022). "Subsequently, we assessed whether PIWIL4 expression could predict the effect of cancer immunotherapy by the TIDE platform." (PMID 36160408, 2022).
cancer (continued). "PIWIL4 belongs to the Argonaute family of proteins, which are involved in the development of organisms and maintenance of germline stem cells and that they are ectopically expressed in multiple forms of cancer." (PMID 33193605, 2020). "Based on a meta-analysis of TCGA and GTEx data, we found that PIWIL1 presents unique features among PIWILs, as PIWIL2 and PIWIL4 are frequently deregulated in cancers but are also expressed in several normal tissues, while PIWIL1 is almost absent in non-transformed tissues." (PMID 31694219, 2019). "The positive expression rate of Piwil4 in the cell nucleus of carcinoma tissue was 84.52% (71/84), significantly higher than that in the cytoplasm [63.1% (53/84); chi-square test, P = 0.002], but the fluorescence intensity in the nucleus was weaker than that in the cytoplasm." (PMID 27894076, 2017). "However, the difference in expression level for PIWIL1 versus PIWIL2 and PIWIL4 contributing to better patient outcome was expected given the difference we observed when comparing their expression in benign and malignant tumors as well as low grade OC versus high grade OC." (PMID 33374923, 2020). "In MDA-MB-231 cells derived from triple-negative breast cancer, PIWIL4 was reported to be able to upregulate the TGF-β, MAPK/ERK, and FGF pathways, which resulted in increased migration, proliferation, and survival of cancer cells." (PMID 39596284, 2024). "Apparently, as PIWIL4 expression elevated, the IC50 of INK-128, entosplenitib and Everolimus against cancer cells was lower." (PMID 36160408, 2022). "This family contains four subtypes which any of them has a different role in cancer cells (PIWIL1 or HIWI, PIWIL2, PIWIL3, and PIWIL4)." (PMID 34193172, 2021). "Our comprehensive analysis revealed a more differentiated pattern where PIWIL1, MAEL and HENMT1 had increased expression, while PIWIL2, PIWIL4 and TDRD1 had decreased expression when comparing benign and malignant tumor samples." (PMID 33374923, 2020). "Gene expression analyses revealed that, given its high expression among cancers studied and consistent overexpression in most AML patients, PIWIL4 could be a potential vulnerability that could be exploited as a therapeutic target in AML." (PMID 39188528, 2024). "Interestingly, ASPM was found in EV derived from serum, urine, and different types of cancer cells; FANCD2 in EV of serum, urine and CRC cells; and PIWIL4 (a canonical RBP) was also found in serum, urine and CRC cells." (PMID 38903178, 2024). "The scarce information about PIWIL4 in human cancer does not provide support for its use as a biomarker in cancer." (PMID 38303021, 2024). "Moreover, PIWIL4 inhibits MHC class II expression, which may assist cancer cells to avoid immune recognition and response." (PMID 31399034, 2019). "Interestingly, the expression of PIWIL4 (both mRNA and protein) as well as that of a transcription promoter-binding protein SUPT5H, were found significantly upregulated in intrahepatic CCA, and could be potentially used as prognostic markers for this cancer." (PMID 38903178, 2024). "We could detect no expression of paralogues in H460, with A2780 expressing PIWIL2 and relatively low levels of PIWIL4; however, the levels of neither were significantly altered by TEX19 depletion, suggesting that TEX19 regulation of PIWI gene expression may not be universal in all cancer cell types." (PMID 28446200, 2017).